RPN2 (ribophorin II)
Diseases named in the same sentence as RPN2 in open-access papers (continued):
Sharing a sentence is not in itself a finding about the gene and the disease.
glioma (continued). "Next, targets of miR-378e were explored and here we first confirmed RPN2 as a functional target of miR-378e in glioma." (PMID 31888753, 2019). "Knockdown of circNFIX inhibits progression of glioma in vitro and in vivo by increasing miR-378e and decreasing RPN2, providing a novel mechanism for understanding the pathogenesis of glioma." (PMID 31888753, 2019). "Moreover, RPN2 regulated glioma development and mediated temozolomide sensitivity through Wnt/β-catenin pathway." (PMID 36118855, 2022). "Taken together, our results suggest that RPN2 may be a crucial prognostic factor, and that the miR181c/RPN2/wnt/β-catenin axis might act as a novel therapeutic target for glioma." (PMID 33087705, 2020). "To determine the expression profile of RPN2 in glioma clinical samples, we first analyzed two TCGA datasets, GBM 29 (containing 154 GBM samples and 5 normal tissues), and GBMLGG14 (containing 5 normal tissues, 516 lower grade, 161 GBM, and 27 recurrent samples), with different histological types." (PMID 33087705, 2020). "Furthermore, we analyzed the CGGA dataset and found that RPN2 expression was positively correlated with the β-catenin expression in both primary and recurrent gliomas." (PMID 33087705, 2020). "Besides, the western blot and RT-PCR analysis of 7 glioma cell lines found that RPN2 was upregulated in GBM cells compared with the lower grade glioma cell line H4." (PMID 33087705, 2020). "Besides, a recent study of glioma found that RPN2 repressed the radiosensitivity of glioma cells by activating STAT3 signal transduction." (PMID 33087705, 2020). "Similarly, qRT-PCR assay in our study also displayed high expression of RPN2 in glioma tissues and cells compared with that in corresponding controls." (PMID 31888753, 2019). "In addition, GERIA online analyzed 10 abnormally expressed genes in glioma tissues, in which RPN2 was remarkably up-regulated in tumor tissues compared with that in normal group." (PMID 31888753, 2019). "This study using western blot assay validated that circNFIX could promote RPN2 expression by competitively sponging miR-378e, uncovering the ceRNA network of circNFIX/miR-378e/RPN2 in glioma." (PMID 31888753, 2019). "Silencing circNFIX decreased glioma xenograft tumor growth by regulating miR-378e/RPN2 axis." (PMID 31888753, 2019). "Therefore, we speculate that RPN2 might be a significant treatment target and prognostic factor for glioma, especially GBM." (PMID 33087705, 2020). "However, the studies of the role of RPN2 in glioma have rarely been reported." (PMID 33087705, 2020). "Six out of eight genes namely, DERL2, RPN2, SEC13, SEC61A1, SEC61B and STT3A were interacting, and were combined into ER stress and UPR-driven aging-related tumor aggressiveness in glioma (ESURATAG) gene signature." (PMID 40718795, 2025). "In our study, we first analyzed TCGA, CGGA and GEPIA databases and found that RPN2 was markedly upregulated in primary and recurrent GBM, which conferred a poor prognosis in glioma patients." (PMID 33087705, 2020). "Hence, we hypothesized that RPN2 might be also as a carcinogenic gene in glioma." (PMID 31888753, 2019). "We identified ER stress and UPR as key aging-related mechanism behind tumor aggressiveness in gliomas, and developed a six gene “ER Stress and UPR-driven Aging-related Tumor Aggressiveness in Glioma” (ESURATAG) gene signature, comprising DERL2, RPN2, SEC13, SEC61A1, SEC61B, and STT3A." (PMID 40718795, 2025). "In the present study, by performing experiments and bioinformatics analysis, we found that RPN2 was markedly elevated in glioma specimens compared with normal controls, and its upregulation was significantly linked to WHO grade and poor prognosis." (PMID 33087705, 2020). "Hence, we, for the first time, revealed the critical regulatory role of RPN2 on miR-181c-mediated wnt signaling inactivation and TMZ sensitivity in glioma." (PMID 33087705, 2020).
glioma (continued). "Accordingly, these results reveal that miR-181c inhibits glioma proliferation and enhances TMZ chemosensitivity, at least partially via RPN2, highlighting that miR-181c/RPN2/wnt axis may play significant roles in GBM progression and TMZ resistance." (PMID 33087705, 2020). "Besides, the exact role of RPN2 in glioma progression was absent in the present study, which should be explored in future." (PMID 31888753, 2019). "Notably, other than RPN2, which has been shown to promote radioresistance via upregulating STAT3 signaling in gliomas, none of the genes in ESURATAG-GS have been studied in the context of glioma, highlighting the novelty of our findings." (PMID 40718795, 2025).
colorectal cancer (11 papers, 2015 to 2022). A primary or metastatic malignant neoplasm that affects the colon or rectum. "Herein, we reveal that downregulation of RPN2, which may be a crucial regulator of N-linked glycosylation in cancer cells and drug-resistant cancer cells, promoted the progression of colorectal cancer (CRC) cell cycle and proliferation in vitro and in vivo." (PMID 29069815, 2017). "Furthermore, RPN2 protein expression evaluated by immunohistochemistry in 78 independent (stage I–IV) colorectal cancer tissues, exhibited a significant association with stage III/IV tumors, distant metastasis, and poor differentiation." (PMID 26388988, 2015). "Similar studies later reported that the downregulation of RPN2 inhibits cell proliferation and further suppresses cell invasion and migration in colorectal cancer cells and in non-small-cell lung cancer cells." (PMID 34575229, 2021). "Integrated transcriptional profiling and genomic analyses reveal that ribophorin II is a promising biomarker in colorectal cancer and promotes colorectal cancer proliferation via regulating the glycosylation status of EGFR." (PMID 34512323, 2021). "RPN2 expression correlates with osteosarcoma, gastric adenocarcinoma and colorectal cancer." (PMID 33692975, 2021). "Although the molecular mechanisms underlying the abnormal expression of RPN2 in various cancer cells are unknown, RPN2 has been shown to be a target gene of microRNA-128 in colorectal cancer cells." (PMID 31810196, 2019). "A previous study demonstrated that, in colorectal cancer, phosphorylation levels of STAT3 and JAK2 were inhibited by RPN2 siRNA 28, indicating that the JAK/STAT pathway was positively correlated with RPN2 expression." (PMID 31743606, 2020).
gastric cancer (10 papers, 2014 to 2022). A primary or metastatic malignant neoplasm involving the stomach. "Next, RPN2's oncogene role has been found in esophageal squamous cell carcinoma, osteosarcoma, gastric cancer, and HCC." (PMID 36072976, 2022). "Our group previously found that downregulation of ribophorin II alleviates the resistance of gastric cancer cells to multiple chemotherapeutic agents." (PMID 34512323, 2021). "If RPN2 expression cannot be observed in advanced gastric cancer biopsy tissue, DCS regimen will be performed with preoperative chemotherapy." (PMID 29632637, 2018). "We also showed correlation between RPN2 expression and P-gp expression in advanced gastric cancer tissue." (PMID 29632637, 2018). "And high expressed RPN2 had a significantly lower 5-year survival rate and higher recurrence rate compared to the gastric cancer cases with low RPN2 expression." (PMID 29632637, 2018). "We confirmed a significantly correlation between RPN2 expression and P-gp expression in advanced gastric cancer biopsy tissue." (PMID 29632637, 2018). "And, we also showed that RPN2 expression had a significantly relationship with tolerance to docetaxel and cisplatin in gastric cancer cell in vitro." (PMID 29632637, 2018). "In multivariate analysis, we confirmed that expression of RPN2 and P-gp were independent factors of prediction of preoperative chemotherapy effect in gastric cancer." (PMID 29632637, 2018). "Of the 40 patients with advanced gastric cancer, we found 47.5% (19 out of 40) of patients were member of the group of RPN2 positive and 52.5% (21 out of 40) were member of the group of RPN2 negative." (PMID 29632637, 2018). "There is very little new knowledge about between expression of RPN2 and tolerance to docetaxel and cisplatin in gastric cancer." (PMID 29632637, 2018). "We found that expression of RPN2 had a significantly relationship with tolerance to docetaxel and cisplatin in gastric cancer cell lines." (PMID 29632637, 2018). "We also examined sensitivity of RPN2-knockout gastric cancer cells by genome editing to docetaxel and cisplatin." (PMID 29632637, 2018). "In the present study, RPN2 expression was analyzed in seven gastric cancer cell lines by western blot analysis." (PMID 25789057, 2015). "Utilizing gastric cancer cell lines as a model, the present study was undertaken to elucidate the role of RPN2 in the response of cells to six common chemotherapeutic agents." (PMID 25789057, 2015). "It was also found that RPN2 depletion increased anticancer drug-mediated cytotoxicity in gastric cancer cell lines." (PMID 25789057, 2015). "The RPN2 protein level was markedly downregulated by RPN2 siRNA after 72 h in the tested gastric cancer cell lines." (PMID 25789057, 2015). "There is little current information regarding RPN2 expression in gastric cancer or a possible correlation between its expression and responses to clinical anticancer drugs." (PMID 25789057, 2015). "The present study aimed to evaluate RPN2 expression in gastric cancer and to examine the possible correlation between RPN2 expression and the response of cells to clinical anticancer drugs, which has received little research attention at present." (PMID 25789057, 2015). "In addition, gastric cancers with high RPN2 expression have exhibited dramatically higher recurrence rates and lower 5-year survival rates relative to those with low expression." (PMID 32404045, 2020). "RPN2 expression in upper endoscopic biopsy tissues can be an effective predictive biomarker for the treatment outcome to docetaxel and cisplatin combination preoperative chemotherapy in advanced gastric cancer." (PMID 29632637, 2018). "We inquired whether RPN2 expression in advanced gastric cancer biopsy tissues may be a predictive biomarker for docetaxel and cisplatin combination preoperative chemotherapy." (PMID 29632637, 2018). "RPN2 expression was observed in 19 of 40 gastric cancer cases." (PMID 29632637, 2018).
gastric cancer (continued). "Also in vitro, we indicated that RPN2 expression reflected docetaxel and cisplatin sensitivity in gastric cancer cell lines." (PMID 29632637, 2018). "Accordingly, the current study used the AGS, SCM-1, TMK-1 and MKN-45 gastric cancer cell lines to investigate whether RPN2 expression is a candidate target for chemotherapy in gastric cancers, one of the most frequent human cancers worldwide." (PMID 25789057, 2015). "However, the predictive value of RPN2 expression in cancer therapy is questionable in gastric cancer models." (PMID 25789057, 2015). "However, little is known about the correlation between RPN2 expression and the response of gastric cancer cells to clinical anticancer drugs." (PMID 25789057, 2015). "Finally, RPN2 expression of upper endoscopic biopsy tissues can be predictive biomarker of sensitivity to docetaxel and cisplatin combination preoperative chemotherapy in advanced gastric cancer patients." (PMID 29632637, 2018). "Notably, RPN2 expression was similar at the transcriptional level in all seven gastric cancer line." (PMID 25789057, 2015). "Therefore, we tested whether RPN2 depletion could have a synergistic effect in S100A4-knockdown gastric cancer cells." (PMID 25310523, 2014). "We analyzed correlation between RPN2 and P-gp, ABCG2, or MRP1 expression in gastric cancer biopsy tissue in manner of immunohistochemical method." (PMID 29632637, 2018). "In another study, RPN2 mediated chemo-sensitivity was mediated by P-gp protein expression, which was downregulated after cisplatin treatment in gastric cancer cells without RPN2." (PMID 32404045, 2020). "It was demonstrated that in patients with advanced esophageal squamous cell carcinoma and in those with advanced gastric cancer, the RPN2-negative group had better pathological and clinical responses to docetaxel-based chemotherapy than the RPN2-positive group." (PMID 34575229, 2021). "RPN2-negative patients with advanced gastric cancer also showed significantly higher PFS and OS." (PMID 34575229, 2021). "Taken together, these data indicate that RPN2 expression may not be a viable, stand-alone target for gastric cancer therapy." (PMID 25789057, 2015).
colon carcinoma (7 papers, 2019 to 2024). "Consistent with our study, the activation of STAT3 by RPN2 was found in other types of cancers, including colon carcinoma, hepatocellular carcinoma." (PMID 32404045, 2020). "RPN2 was reported to regulate colon cancer cell proliferation through mediating the glycosylation of EGFR, which affectes the EGFR/ERK signaling pathways." (PMID 32404045, 2020).
esophageal squamous cell carcinoma (6 papers, 2013 to 2022). Esophageal squamous cell carcinoma (ESCC) is a type of esophageal carcinoma (EC) that can affect any part of the esophagus, but is usually located in the upper or middle third. "Silencing of human RPN2 also decreases drug resistant breast tumor and esophageal squamous cell carcinoma growth, indicating that RPN2 may function in cell division and be an important cancer therapeutic target." (PMID 24130834, 2013).
esophageal cancer (5 papers, 2014 to 2024). A primary or metastatic malignant neoplasm involving the esophagus. "RPN2 expression levels in esophageal cancer tissues were positively associated with differentiation and tumor node metastasis (TNM) stage." (PMID 30940778, 2019). "RPN2 levels in esophageal cancer tissues were positively associated with differentiation and tumor node metastasis (TNM) stage." (PMID 30940778, 2019). "Our results show that decreased expression of RPN2 significantly reduces cell migration and invasion of esophageal cancer cells." (PMID 30940778, 2019). "In order to examine the role of RPN2 in tumor growth in esophageal cancer, CP-D and CP-C cells were transfected with siRNP2 and negative control plasmid." (PMID 30940778, 2019). "To evaluate the function of RPN2 in esophageal cancer, we quantified RPN2 expression in esophageal cancer tissue and adjacent normal esophageal tissue by RT-PCR and Immunohistochemistry (IHC) analysis." (PMID 30940778, 2019). "RPN2 expression in esophageal cancer tissues was significantly increased compared with normal tissue (P<0.001)." (PMID 30940778, 2019). "In the present study, we found that knockdown of RPN2 effectively inhibited cell proliferation of esophageal cancer cells." (PMID 30940778, 2019). "Silencing RPN2 effectively inhibited cell proliferation of esophageal cancer cells in vitro and in vivo." (PMID 30940778, 2019). "Then, we detected the expression levels of RPN2 in a human esophageal epithelial cell line (Het-1A) and in two esophageal cancer cell lines (CP-D and CP-C) by RT-PCR and Western blot." (PMID 30940778, 2019). "In our study, we report for the first time that RPN2 expression is significantly increased in the esophageal cancer tissue compared with normal tissue." (PMID 30940778, 2019). "First, we found abnormally increased expression of RPN2 in esophageal carcinoma tissues and cell lines." (PMID 30940778, 2019). "In summary, we report that elevated RPN2 expression was seen in esophageal cancer and that RPN2 could promote cell proliferation, migration, and invasion of esophageal cancer cells." (PMID 30940778, 2019). "Furthermore, the expression of RPN2 was increased significantly in esophageal cancer cell lines compared with normal cells." (PMID 30940778, 2019). "The results indicate that overexpression of RPN2 might promote cell proliferation in esophageal cancer." (PMID 30940778, 2019). "In the present study, we explore the biological role of RPN2 in esophageal cancer." (PMID 30940778, 2019). "Silencing of RPN2 increased the sensitivity of esophageal cancer cells to docetaxel." (PMID 25181275, 2014). "The results indicate that RPN2 might exert tumor-promoting action in esophageal cancer." (PMID 30940778, 2019). "In addition, the underlying mechanism by which RPN1 and RPN2 regulates the progression of esophageal cancer is still not well known." (PMID 30940778, 2019). "The results reveal that RPN2 knockdown might attenuate tumor metastasis in esophageal cancer." (PMID 30940778, 2019). "First, we found that the expression of RPN2 was higher in esophageal cancer tissues than in adjacent non-tumor tissues, and negatively correlated with E-cadherin expression." (PMID 30940778, 2019). "The mRNA expression of E-cadherin in esophageal cancer tissues was also examined, and E-cadherin expression showed a negative correlation with RPN2 expression." (PMID 30940778, 2019).